S100A10 (S100 calcium binding protein A10)
Diseases named in the same sentence as S100A10 in open-access papers (continued):
Sharing a sentence is not in itself a finding about the gene and the disease.
tumor (continued). "We showed that reduction of Plgrkt, but not S100a10, in PDAC tumor cells significantly reduced metastatic potential." (PMID 37971174, 2024). "In the main tumor components without TB/PDC, neither distinct membranous positivity for S100A10 nor for ANX A2 was seen, except for a reaction at their luminal surface." (PMID 33160379, 2020). "In the main tumor components without TB/PDC, neither distinct membranous positivity for S100A10 nor for ANX A2, were noted except for a reaction at their luminal surface (data not shown)." (PMID 33160379, 2020). "S100A10-null macrophages are not able to stimulate angiogenesis and LLC tumor growth in the S100A10-null mice." (PMID 30572596, 2018). "However, we have recently established that S100A10, and not annexin A2, is responsible for not only promoting the reported macrophage plasminogen-mediated matrix invasion and degradation but also the infiltration of tumor-promoting macrophages into tumor sites." (PMID 23519104, 2013). "Several genes thought to play a role in the processes of invasion, tumour progression and metastasis (MME, STAT3, DCBLD2, S100A10, CD9, S100A8) were highly downregulated in the NE vs the non-NE tumour group." (PMID 18827820, 2008). "Thus, its interesting to note that several genes thought to play a role in the processes of invasion, tumour progression and metastasis (MME, STAT3, DCBLD2, S100A10, CD9, S100A8) were highly downregulated in the NE vs the non-NE tumour group." (PMID 18827820, 2008).
cancer (84 papers, 2008 to 2025). A tumor composed of atypical neoplastic, often pleomorphic cells that invade other tissues. "In particular, S100B was found to be linked to better survival in 13 cancers, while S100A10 was associated with worse survival in 19 cancers." (PMID 38684596, 2024). "S100A10 expression has been associated with the hallmarks of cancer in several cancers, such as the brain, breast, lung, colorectal, kidney, ovarian, acute lymphoblastic leukemia, and pancreatic." (PMID 37892132, 2023). "The upregulation of S100A10 was also significantly associated with high-stage cancer (T3-T4) and high-grade cancer." (PMID 34944416, 2021). "As a plasminogen receptor, S100A10 which is closely associated with the invasion and metastasis of malignant tumors, was highly expressed in PGCCs with their daughter cells." (PMID 34336846, 2021). "We reported that Kaplan–Meier survival analysis showed that high levels of S100A10 were significantly associated with both shorter overall survival (HR = 3.34) and recurrence-free cancer (HR = 2.27)." (PMID 34944416, 2021). "Kaplan–Meier survival analysis showed that high levels of S100A10 were significantly associated with both shorter overall survival (HR = 3.34, p < 0.0001) and recurrence-free cancer (HR = 2.27, p < 0.001)." (PMID 33297495, 2020). "Previous studies have reported that the upregulation of S100A10 is associated with cancer metastasis." (PMID 31739800, 2019). "S100A10 expression is increased in many other cancers and is generally associated with a poor prognosis." (PMID 30572596, 2018). "The plasminogen receptor S100A10 is a member of the S100 family of proteins and its expression has been linked to enhanced plasminogen activation and invasion of cancer cells." (PMID 30237490, 2018). "MAP3K1 encodes a MEK kinase involved in the regulation of cell proliferation, SCARB1 plays an important role in the regulation of cell homeostasis by maintaining the level of cholesterol available in fibroblasts for androgen synthesis, and S100A10 controls migration of cancer-associated macrophages." (PMID 35740605, 2022). "Moreover, the fact that the stabilization of S100A10 with the K47E mutation significantly promoted cancer cell invasion in vitro and in vivo indicates the crucial role of S100A10 succinylation." (PMID 30394687, 2019). "S100A10 has been linked to play a key role in proliferation in many different types of cancers." (PMID 30572596, 2018). "In particular, S100A4, S100A6, S100A7 and S100A10 have been found to be overexpressed in some cancer types, and could be associated with aggressive cancer phenotype." (PMID 27008379, 2016). "Two Annexin A2 monomers bridged by an S100A10 homodimer are known to form a multifunctional membrane-associated heterotetramer, which has been implicated in membrane trafficking events and membrane-cytoskeletal connection relating to cell motility and drug-resistance in human cancers." (PMID 32154176, 2020). "Through correlation analysis, we observed that LAD1 expression levels were statistically associated with several cancer-related genes, including SFTPB, S100A6, CEACAM6, KRT19, S100A10, ANXA2, S100A11, and CAPN2." (PMID 41423496, 2025). "The outcome of our study regarding S100A10’s effect on tumoral growth is in disagreement with other studies performed in vitro where a deleterious role of S100A10 was pinpointed in cancer hepatocyte cell lines as well as in other cancer forms." (PMID 40841353, 2025). "S100A10 has been shown to play a crucial role in promoting invasion and metastasis in several types of cancer by stimulating plasmin-mediated degradation of the extracellular matrix." (PMID 39934880, 2025). "Our present findings provided further evidence of the pro-cancer role of S100A10 in PTC, as indicated by its correlation with extrathyroidal extension, nodal metastasis, and the risk of recurrence." (PMID 39934880, 2025).
cancer (continued). "Among the myriad of Pg receptors, Histone H2B, HMGB1, alpha-enolase, plasminogen-Rkt, cytokeratin 8, and S100A10 (p11) have been extensively characterized for their role as Pg receptors in cancer progression." (PMID 41463352, 2025). "S100A10 (p11) is a calcium-binding protein involved in cell proliferation, differentiation and migration, contributes to tumorigenesis, in various cancers." (PMID 41050670, 2025). "Our laboratory and others have established that S100A10 plays an oncogenic role in multiple cancer types." (PMID 41463352, 2025). "Beyond its canonical role in plasmin regulation, S100A10 also regulates the expression of cell-surface receptors and ion channels, contributing to its pleiotropic effects in cancer." (PMID 41463352, 2025). "Our signature genes, S100A10/p11, and CSNK1A1, are intricately linked to the development of various diseases and cancers." (PMID 39660117, 2024). "Cluster 25 (CD163+ApoE+) macrophages expressed S100A4 and S100A10, while Cluster 18 (ApoE+ki67+) cancer cells expressed high levels of ApoE, Ki-67, and vimentin." (PMID 39695088, 2024). "Experimental validation further supports S100A10 as a potential prognostic marker for this cancer type." (PMID 39840058, 2024). "Cluster 23 (CD31+ApoE+ EC cells) also exhibited a significant spatial interaction with Cluster 18 cancer cells by S100A10 and Thbs1 secretion." (PMID 39695088, 2024). "S100A10 has been reported to be highly expressed in various cancer tissues, including HCC, and promotes the proliferation and migration of cancer cells." (PMID 39117605, 2024). "This prior evidence highlights the important roles that S100A10 can play in cancer, emphasizing its relevance as a target for therapeutic intervention efforts." (PMID 37781076, 2023). "Since S100A10 is a multi-functional protein, it plays both plasminogen-dependent and independent roles in the progression of cancer, depending on the cellular context." (PMID 37892132, 2023). "In the cancer cell lines, the transcript levels of S100A10 were among the highest of all S100s, with a mean Ct = 4.15 +/− 0.88." (PMID 37627239, 2023). "Our findings lay a firm foundation for future studies aiming to clarify the role of S100A10 in CESC and determine its potential as a diagnostic or therapeutic target for this type of cancer." (PMID 37781076, 2023). "In vitro and xenograft experiments supported the pro-oncogenic role of S100A10, providing further evidence of its significance in this specific cancer context." (PMID 37781076, 2023). "One potential explanation is the role S100A10 plays in promoting cancer cell stemness, which has implications for promoting chemoresistance." (PMID 37892132, 2023). "This S100A10-mediated protease activation is utilized by highly motile cells, such as metastatic cancer cells and macrophages, to facilitate its migration through the ECM." (PMID 37892132, 2023). "Second, the cancer cells also secreted S100A10 in the extracellular vesicles (EVs), which promoted motility, invasion, and metastasis." (PMID 37892132, 2023). "Stromal protein expression changed primarily during the transition from SBT to LGSC (629 differentially expressed proteins), including the upregulation of ANXA2 and its regulator S100A10, which play a central role in cancer cell proliferation." (PMID 38014221, 2023). "S100A10 has been demonstrated to have a certain value in the diagnosis, treatment, and prognosis assessment of a variety of cancers since being first identified in 1985." (PMID 36612197, 2022). "In this regard, S100A10 was described to promote invasiveness and metastasis dissemination in different types of cancers, including in in vitro transformed hepatocytes and in Hep3B mouse xenografts." (PMID 36232334, 2022). "This oncogenic function of S100A10 was associated with its capability to form complexes with ANXA2, another potent oncogene in many cancers." (PMID 36232334, 2022).
cancer (continued). "As a member of the S100 protein family, S100A10 regulates multiple biological functions related to cancer progression and metastasis." (PMID 36612197, 2022). "Four gene markers, BARD1 (BRCA-associated RING domain 1), SOD2 (superoxide dismutase 2), S100A10, and TSC22D3 (TSC22 domain family member 3), were found to be the targets of several approved cancer drugs." (PMID 36430822, 2022). "The data showed that S100A4, S100A14 and S100A16 were significantly higher in PDAC tissues compared with their counterparts, but the protein level of S100A2, S100A6 and S100A10 were similar between cancer tissues and their counterparts." (PMID 34530774, 2021). "In group III, S100A10 expression was located in both the cytoplasm and nucleus of cancer cells (-e)." (PMID 34336846, 2021). "Using cultured cell models of cancer, we have shown that S100A10 is regulated by Smad4-dependent TGFβ1-mediated signaling and FOXC2-mediated PI3K signaling." (PMID 34944416, 2021). "According to genomic data from the National Cancer Institute (NCI), across 33 different types of cancer, S100A10 mRNA was the third-highest in PDAC." (PMID 34944416, 2021). "First, we examined the effect of blocking the expression of the S100A10 subunit with several well-established cancer cell models." (PMID 34944416, 2021). "The involvement of HIF1α links S100A10 expression with hypoxic conditions characteristic for many cancer tissues." (PMID 34356598, 2021). "These investigators observed that S100A10 was one of the most highly upregulated proteins in the metastasized cancer cells compared to the tumor cancer cells." (PMID 34944416, 2021). "The membrane-localized S100A10 promotes cancer invasion by regulating tissue plasminogen activator activity and plasmin generation." (PMID 34336846, 2021). "S100A10 in the cell membrane and cytoplasm plays an important role in the infiltration and invasion of malignant tumors." (PMID 34336846, 2021). "The findings indicated the oncogene activity of S100A10 in malignant tumors of the digestive system." (PMID 33324631, 2020). "S100A10, a member of the S100 protein family, is also expressed in various cells, including cancer cells." (PMID 33160379, 2020). "S100A10 is overexpressed in various cancers and plays a role in facilitating cell invasiveness by regulating pericellular proteolysis." (PMID 32457792, 2020). "S100A10 can interact with the Ras oncogene, contributing to the development, invasion and metastasis of cancer." (PMID 31949486, 2020). "The novel oncogene S100A10 has been reported to be involved in cancer cell proliferation, invasion and metastasis." (PMID 31739800, 2019). "Our research group has previously demonstrated that S100A10 (p11) is a receptor for the pro‐protease plasminogen and can drive cancer cell invasion by mediating the conversion of plasminogen into the active protease, plasmin." (PMID 30009399, 2018). "To exclude the possibility that the observed increases in S100A10 were limited to A549 cells, we treated multiple cancer cell types known to undergo EMT in response to TGFβ1 treatment." (PMID 30237490, 2018). "Collectively, these studies strongly indicate that S100A10 is a central player in facilitating uPA‐mediated cleavage of plasminogen in KRAS‐transformed cancer cells." (PMID 30009399, 2018). "In cancer cells, increased annexin A2 and S100A10 expression result in increased plasmin production, which leads to the degradation of the ECM and activation of MMPs, thereby enabling the invasion of surrounding organs or local vasculature." (PMID 30572596, 2018). "Subsequent assessment of cancer cell invasion revealed that S100A10 depletion reduced the ability of Panc‐1 cells (by 64%) to pass through the ECM‐dense matrigel even in the presence of exogenous plasminogen (+Pg) compared to scramble control cells." (PMID 30009399, 2018). "In conclusion, S100A10 has been shown to play an important role in promoting pro-tumorigenic behavior in many cancers." (PMID 30572596, 2018).
cancer (continued). "S100A10 expression promotes the migration of non-small cell lung cancer (NSCLC) A549 cancer cells in vitro." (PMID 30572596, 2018). "Increased expression of annexin A2 and S100A10 in cancer cells leads to increased levels of plasmin—which promotes the degradation of the extracellular matrix—increased angiogenesis, and the invasion of the surrounding organs." (PMID 30572596, 2018). "The annexin A2/S100a10 complex has been reported as being upregulated in many cancers, including HCC." (PMID 28179399, 2017). "In order to determine if there was a relationship between oncogenic RAS expression and S100A10 levels in clinically relevant cancer cells, we analyzed by western blotting, a panel of different cancer cell lines of which some express oncogenic RAS." (PMID 27351226, 2016). "To further confirm that KRAS activity is important for the regulation of S100A10 expression in cancer cells derived from human tumors, we depleted KRAS from A549 and MiaPaca2 cells." (PMID 27351226, 2016). "It was striking to observe that cells derived from cancers that show high mutational rates for KRas, such as colon (HCT 116), lung (A549) and pancreatic (MiaPaca2) cancers, have high levels of expression of S100A10." (PMID 27351226, 2016). "In the present report we show a significant relationship between oncogenic KRAS expression and enhanced levels of S100A10 in a panel of different human cancer cell lines." (PMID 27351226, 2016). "Conversely, annexin A2, well known to have multiple functions and biological role in cancer cells, also requires S100A10 for its action and translocation to the cell surface." (PMID 24851084, 2014). "Accumulating evidence delineates a correlation between the deregulation of annexin A2 expression and tumorigenesis in many cancers but disregard the possible role of S100A10." (PMID 23519104, 2013). "The plasminogen receptor S100A10 is found overexpressed in many cancer cells, and seems to play an important role in cancer cell invasiveness and metastasis." (PMID 18827820, 2008). "Study found a significant role for S100A10 in diversified malignant tumors." (PMID 39128058, 2024). "The role of the S100A10 gene in various cancers has garnered significant attention." (PMID 39117605, 2024). "S100A10 has also recently been tied to the incidence and progression of various forms of cancer." (PMID 37781076, 2023). "S100A10 can respond to a variety of signals to maintain and accelerate cancer cell metabolism." (PMID 37892132, 2023). "S100A10 is involved in various cellular processes, regulates plasminogen activation and has been shown to suppress pro-apoptotic capacity of Bcl-2-associated death protein (BAD), which is suggested to have anti-apoptotic function in cancer cells." (PMID 36230614, 2022). "S100A10 is correlated with drug resistance to various cancer types." (PMID 36430822, 2022). "Finally, an original function in cancer was described for the extra-cellular S100A10 isoform in plasmin biogenesis through its tetramerization with ANXA2." (PMID 36232334, 2022). "S100A10 may have anti-apoptotic effects in cancer cells, interacting with Bad and impeding its pro-apoptotic activity." (PMID 36685937, 2022). "It is indicated that S100A10 may promote the invasiveness and metastasis of these cancer cells through an ANXA2-independent pathway." (PMID 36612197, 2022). "In many cancers, S100A10 has been demonstrated to play a vital role in promoting tumorigenesis." (PMID 35437508, 2022). "S100A10 plays an important role in the progression of various cancers." (PMID 34804125, 2021). "Expression of GRHL2 is increased in many cancers and the same applies to S100A10." (PMID 34356598, 2021). "The first demonstration of the potential involvement of AIIt in cancer was our observation, in 2003, that knockdown of S100A10 in HT1080 cells resulted in concomitant decreases in cellular plasmin production, extracellular matrix degradation, and cellular invasiveness." (PMID 34944416, 2021).